AIM2 (absent in melanoma 2)
Diseases named in the same sentence as AIM2 in open-access papers (continued):
Sharing a sentence is not in itself a finding about the gene and the disease.
osteosarcoma (9 papers, 2022 to 2025). A usually aggressive malignant bone-forming mesenchymal neoplasm, predominantly affecting adolescents and young adults. "The PI3K/AKT/mTOR pathway is implicated in AIM2-mediated proliferation, invasion, migration, and apoptosis in osteosarcoma cells." (PMID 36568515, 2022). "We also found that AIM2 was highly methylated in patients with high-risk osteosarcoma and was expressed lower in metastatic osteosarcoma cells, which was consistent with the point that loss of AIM2 promotes cancer metastasis." (PMID 36072791, 2022). "A separate investigation involving various cancer cell lines revealed that AIM2 was expressed at low levels in osteosarcoma cell lines." (PMID 39600708, 2024). "While, researchers also have found that AIM2 suppresses tumor cell malignant biological properties by inactivating PI3K/AKT/mTOR pathway in osteosarcoma cells." (PMID 39222064, 2024). "The findings suggest that AIM2 suppresses osteosarcoma progression through the inactivation of the PI3K/AKT/mTOR signaling pathway." (PMID 39600708, 2024). "With this approach, we identified expression of AIM2 and PKIB as being valuable tools to assess risk in patients with osteosarcoma." (PMID 36072791, 2022). "Therefore, according to this unique study, the AIM2 inflammasome seems to play an anti-tumor role in osteosarcoma, most likely via the PI3K/AKT/mTOR signaling pathway." (PMID 40002808, 2025). "AIM2 inhibited the progression of osteosarcoma by inhibiting PI3K/AKT/mTOR signaling pathway." (PMID 39600708, 2024). "In this study, we evaluated DNA methylation profiles combined with gene expression profiles of 21 patients with metastatic osteosarcoma and 64 patients with non-metastatic osteosarcoma from TARGET database and identified PKIB and AIM2 as hub genes related to the metastasis of osteosarcoma." (PMID 36072791, 2022). "In addition, AIM2 also showed an inhibitory effect on the proliferation, invasion, and migration of osteosarcoma cells by reducing AKT phosphorylation." (PMID 36120327, 2022). "Furthermore, combined clinical profiles analysis showed that the expression of AIM2- and PKIB- related risk scores was significantly related to the overall survival of patients with osteosarcoma." (PMID 36072791, 2022). "Finally, we constructed a nomogram on the basis of AIM2/PKIB expression–based risk score to predict prognosis of the 1-, 2-, 3-, and 5-year OS of patients with osteosarcoma, offering clinical value for prognosis prediction and support osteosarcoma treatment decision process." (PMID 36072791, 2022). "Thus, hub genes of AIM2 and PKIB were selected to construct the risk signature for osteosarcoma." (PMID 36072791, 2022). "The application of activators targeting the PI3K/AKT/mTOR signaling pathway effectively reversed the impact of AIM2 overexpression on the proliferation, apoptosis, invasion, migration, and EMT of osteosarcoma cells." (PMID 39600708, 2024). "Focusing on the six intersection genes and their potential roles, we performed multivariable COX analysis and only identified two hub genes, AIM2 and PKIB, which were related to the metastasis of osteosarcoma." (PMID 36072791, 2022). "The authors found that AIM2 expression was downregulated in osteosarcoma cells at both the transcriptional and protein level; instead, AIM2 overexpression led to the inhibition of proliferation, invasion, migration, and EMT, and induced apoptosis in osteosarcoma cells." (PMID 40002808, 2025). "Notably, the overexpression of AIM2 resulted in the inhibition of proliferation, invasion, migration, and epithelial-mesenchymal transition (EMT) in osteosarcoma cells, while simultaneously promoting pyroptosis." (PMID 39600708, 2024).
osteosarcoma (continued). "Absent in melanoma 2 (AIM2) and Fer-1-like protein 4 (FER1L4) are two osteosarcoma inhibitors, and several studies have found that their overexpression inhibited the PI3K/AKT/mTOR signaling pathway, with an increase in E-calmodulin and a decrease in wave proteins and fibronectin, inhibiting EMT." (PMID 37404761, 2023). "In addition, further analysis together with clinical data showed that AIM2 and PKIB were identified as hub genes related to OS of patients with osteosarcoma." (PMID 36072791, 2022). "We identified that PKIB (protein kinase inhibitor-β) and AIM2 (absent in melanoma 2) were related to the metastasis and survival of osteosarcoma." (PMID 36072791, 2022). "Further analysis on the differences between metastatic and non-metastatic samples revealed six intersection genes—AIM2, RPL22L1, PDPN, PKIB, GZMA, and MDM2—that related to metastasis potential of osteosarcoma and the observed gene expression differences resulted from the changes in methylation." (PMID 36072791, 2022).
cutaneous squamous cell carcinoma (8 papers, 2017 to 2025). "For instance, AIM2 mRNA levels are significantly reduced in prostate adenocarcinoma tissue, possibly linked to interferon signaling pathway activation, while they are upregulated in primary and metastatic cutaneous squamous cell carcinoma cell lines, regulating their growth and invasion." (PMID 38186575, 2023). "The presence of AIM2 in cutaneous squamous cell carcinoma (cSCC) cells is more abundant than in normal skin tissues." (PMID 40386782, 2025). "Elevated expression of AIM2 has been detected in cutaneous squamous cell carcinoma than in normal skin." (PMID 36932407, 2023). "The protein and mRNA expression of AIM2 is increased in cutaneous squamous cell carcinoma cells, and AIM2 was discovered to possibly be involved in the regulation of the cell cycle as well as cell survival and apoptosis." (PMID 36742336, 2023). "Partly through activating autophagy that suppresses AIM2, dihydroartemisinin shows an inhibitory effect on cutaneous squamous cell carcinoma." (PMID 36932407, 2023).
experimental autoimmune encephalomyelitis (8 papers, 2021 to 2024). An autoimmune demyelinating disease of the central nervous system that is produced experimentally in animals by the injection of homogenized brain or spinal cord in Freund's adjuvant. "AIM2 depletion worsens outcomes in murine models of experimental autoimmune encephalomyelitis driven by enhanced type I IFN signaling." (PMID 37216118, 2023). "Additionally, AIM2 interacts with DNA-dependent protein kinase (DNA-PK) to play a protective role against experimental autoimmune encephalomyelitis in microglia." (PMID 38429284, 2024). "Besides TH cells, Treg cells express Aim2, and Aim2 is important for the maintenance of stable suppressive Treg cells in a murine experimental autoimmune encephalomyelitis model." (PMID 35538881, 2022). "Several studies have shown that Aim2 restrains clinical symptoms in experimental autoimmune encephalomyelitis (EAE) mice by stabilising T regulatory (Treg) cells, suggesting that inflammasome‐independent Aim2 participates in the regulation of the CD4+ T‐cell response in autoimmune models." (PMID 35343082, 2022). "Other researches found that AIM2 negatively regulates the DNA-PK-AKT3 in microglia to control neuroinflammation and enhances the stability of T regulatory cells via interacting with the RACK1-PP2A phosphatase complex to restrain AKT phosphorylation in experimental autoimmune encephalomyelitis (EAE)." (PMID 38918243, 2024).
HCMV infection (8 papers, 2017 to 2025). "We proposed that such attenuation of AIM2 inflammasome 24 h post HCMV infection was linked to pUL83." (PMID 28219398, 2017). "AIM2, a cytosolic DNA sensor, plays an important role during infection caused by pathogens with double-stranded DNA; however, its role in human cytomegalovirus (HCMV) infection remains unclear." (PMID 28219398, 2017). "MCMV-infected AIM2-deficient mice were shown to have reduced IL-18 serum levels, and AIM2-deficient THP-1 cells were unable to efficiently control HCMV infection." (PMID 39205246, 2024). "cGAS/STING pathway activation contributes to increased IL-1β secretion after HCMV infection through the upregulation of AIM2." (PMID 34372578, 2021). "In summary, our data indicate that the HCMV tegument protein pUL83 binds to cellular AIM2, which partially contributes to the attenuation of the AIM2 inflammasome proteins 24 h post HCMV infection and reduced activation of caspase-1 and IL-1β." (PMID 28219398, 2017). "We detected an increase in AIM2 protein levels in THP-1 − derived macrophages 3 h post HCMV infection, which gradually increased up to 12 h." (PMID 28219398, 2017). "On the other hand, an AIM2 inflammasome-dependent IL-1β response to murine cytomegalovirus infection was reported in mouse macrophages." (PMID 28369146, 2017). "In our previous study involving THP-1 − derived macrophages, we observed an increase in AIM2 levels at the early stage of HCMV infection; however, 24 h post infection, they returned to the basal level (unpublished data)." (PMID 28219398, 2017). "Previously, we showed an increase in AIM2 protein levels during the early stage of HCMV infection and a decrease 24 h post infection." (PMID 28219398, 2017). "Our data indicate that pUL83 interacts with AIM2 in the cytoplasm during the early stages of HCMV infection." (PMID 28219398, 2017). "Whether HCMV infection is sensed by the AIM2 or the NLRP3 inflammasome, and whether UL83 or UL84 inhibits inflammasome activation, cytokine release, and pyroptosis will have to be clarified in future studies." (PMID 38278864, 2024). "HCMV infection activates the AIM2/caspase-1/IL-1β pro-inflammatory pathway." (PMID 34372578, 2021). "To determine whether pUL83 contributes to the variation in AIM2 levels during HCMV infection, we investigated the pUL83/AIM2 interaction and its impact on the AIM2 inflammasome activation." (PMID 28219398, 2017). "Our findings are supported by results from murine models of gouty arthritis, ulcerative colitis, and cytomegalovirus infection, which suggest that targeting ASC can inhibit the activation of the NLRP3 and AIM2 inflammasome and alleviate inflammation." (PMID 39990234, 2025). "Here, we used clustered regularly interspaced short palindromic repeat (CRISPR)–CRISPR-associated protein 9 (Cas9) genome editing to demonstrate that the dsDNA receptor absent in melanoma 2 (AIM2) is required for secretion of IL-1β following HCMV infection." (PMID 30755509, 2019).
malaria (8 papers, 2009 to 2025). Malaria is a serious and sometimes fatal disease caused by a parasite that commonly infects a certain type of mosquito which feeds on humans. "AIM2 has been reported to play a significant role in various parasitic diseases including malaria and leishmaniasis." (PMID 38559160, 2024). "The higher amount of MyD88-IRF7 dependent type I IFN cytokines in pDCs of Il1r1−/−, Aim2−/−, Nlrp3−/−, and Casp1−/− mice at the early stage of YM infection facilitates anti-malaria adaptive immune response." (PMID 30470758, 2018). "Taken together, these results suggest that malaria gDNA, RNA and hemozoin activate inflammasome through AIM2 and NLRP3 signaling during YM infection." (PMID 30470758, 2018). "During malaria, AIM2 and NLRP3-induced CASP1-dependent inflammasome signaling induces the release of IL-1β in pDCs and activates IL-1 signaling, which induces negative regulator SOCS1 in a MyD88-TRAF3-IRF3-dependent manner and inhibits MyD88-IRF7-dependent type I IFN signaling in pDCs." (PMID 36214572, 2022). "Furthermore, infected erythrocytes can activate both NLRP3 and AIM2 inflammasomes during malaria in vitro stimulation." (PMID 30470758, 2018). "We have previously shown that AIM2 and NLRP3 inflammasomes, as well as caspase-1, are activated in monocytes from malaria patients." (PMID 32929083, 2020). "Mechanistically, we show that AIM2 and NLRP3 inflammasome activation by YM infection produces IL-1β in pDCs and potentially many other cell types, depending upon exposure of malaria." (PMID 30470758, 2018). "Furthermore, it was demonstrated that monocytes from febrile malaria patients express high levels of NLRP3, NLRP12, and AIM2 inflammasome specks, as well as active caspase-118,19." (PMID 32929083, 2020). "Increased abundance of AIM2 (interferon-inducible and neutrophil-related gene), LAP3 (interferon-inducible gene) and WARS (interferon-response gene) found in our study has also been observed to be over-expressed in patients with malaria." (PMID 19903332, 2009). "Although AIM2 and NLRP3 have been identified as sensors of malaria gDNA and hemozoin in vitro, their in vivo function has not been reported." (PMID 30470758, 2018).
oral squamous cell carcinoma (8 papers, 2019 to 2024). "AIM2 expression is also reduced in prostate cancer, whereas it is upregulated in nasopharyngeal and oral squamous cell carcinoma and lung adenocarcinoma." (PMID 31861809, 2019). "It has been reported that the knockdown of AIM2 downregulates nuclear factor κB (NF-κB) expression, resulting in the suppression of cell growth and apoptosis in oral squamous cell carcinoma 26, while the transcription factor NF-κB binds to the BCL2A1 promoter induces its mRNA transcription." (PMID 33391539, 2021). "Knockdown of either AIM2 or IFI16 in oral squamous cell carcinoma cells reduced cell growth." (PMID 32328125, 2020). "IFI16 and AIM2 genes are overexpressed in oral squamous cell carcinomas." (PMID 31861809, 2019). "In oral squamous cell carcinoma (OSCC), AIM2 was overexpressed and ectopic AIM2 expression enhanced OSCC cell proliferation and prevented cell apoptosis." (PMID 33291082, 2020). "Also, regarding PGE2, a recent study indicates the relationship between AIM2 upregulation and activation of the TNFα-NF-κB signaling by showing upregulated AIM2-mediated IL-1β secretion and activation of STAT1/NF-κB-related pathway in oral squamous cell carcinoma cells." (PMID 39290706, 2024).
renal cell carcinoma (8 papers, 2019 to 2025). "In renal cell carcinoma cells, receptor protein AIM2 promotes FOXO3a phosphorylation and proteasome degradation, thereby abating its transcriptional effect on ACSL4 and inhibiting ferroptosis." (PMID 40050614, 2025). "For instance, AIM2 was capable of inhibiting the proliferation, invasion and migration of renal cell carcinoma (RCC) cells by upregulating autophagy-related genes (Bcl-2, Beclin-1, LC3-II and ATG5)." (PMID 31492049, 2019). "Besides, AIM2 was found to trigger renal cell carcinoma progression and sunitinib resistance through FOXO3a-ACSL4 axis-regulated ferroptosis." (PMID 38166970, 2024). "AIM2 inhibits the malignant behavior of renal cell carcinoma by inducing autophagy." (PMID 34680930, 2021). "In renal cell carcinoma (RCC), a separate investigation demonstrated that a conditionally replicating adenovirus containing AIM2 effectively suppressed cell proliferation, induced apoptosis, and hindered lung metastasis by activating the inflammasome pathway." (PMID 39744568, 2025).
Anxiety (7 papers, 2016 to 2025). Intense feelings of nervousness, tension, or panic often arise in response to interpersonal stresses. "It has been demonstrated that AIM2 regulates neuronal morphology, including dendritic growth and axon extension, and influences mouse behaviors, including anxiety and memory." (PMID 37177836, 2023). "Moreover, several investigations have demonstrated that substantial AIM2 inflammasome activation was detected in neurodevelopment, and abnormalities in AIM2 result in anxiety-related behaviors in mice." (PMID 37450925, 2023). "The present study supports the role of MG to modulate NLRP3, NLRC4, and AIM2 inflammasome activation, both in primary cortical microglia and in a mouse model of anxiety and depression, as a potential therapeutic approach to addressing immune-inflammatory-based disorders." (PMID 35740286, 2022). "At the same time, phenolic metabolites represented by Malvidin have beneficial effects on anxiety and depression by targeting and regulating NLRP3, NLRC4 and AIM2 inflammasomes." (PMID 37474898, 2023). "Eda-Dex administration potently attenuated cerebral damage, protected neurological function, attenuated anxiety-like behavior and improved cognitive function by synergistically inhibiting oxidative stress and inflammation through targeting of the NRF2/ARE and NF-κB/AIM2 pathways in CIRI rats." (PMID 40351418, 2025). "In AD, AIM2 inflammasome was demonstrated to act as a mediator in microglial activation, Aβ deposition, and cytokine production, but the knockout of AIM2 in 5XFAD mice did not improve memory and anxiety phenotype or had any beneficial effect on cytokine expression." (PMID 35979366, 2022).
chronic obstructive pulmonary disease (7 papers, 2019 to 2025). A chronic and progressive lung disorder characterized by the loss of elasticity of the bronchial tree and the air sacs, destruction of the air sacs wall, thickening of the bronchial wall, and mucous accumulation in the bronchial tree. "Recent reports imply that the activation of the AIM2 inflammasome or other inflammasomes is a critical event during the severity of asthma and chronic obstructive pulmonary disease (COPD)." (PMID 32121297, 2020). "It is well known that the AIM2 inflammasome is involved in the inflammatory pattern associated with chronic pulmonary diseases, such idiopathic pulmonary fibrosis (IPF), long-Coronavirus Disease 19 (COVID-19) and chronic obstructive pulmonary disease (COPD)." (PMID 40002808, 2025). "In contrast, in patients with chronic obstructive pulmonary disease (COPD), a chronic inflammatory lung disease, both AIM2-mediated canonical and noncanonical inflammasomes participate the IL-1α-induced release of TGF-β in PBMCs." (PMID 37446052, 2023).
gout (7 papers, 2020 to 2026). A condition characterized by painful swelling of the joints, which is caused by deposition of urate crystals. "The AIM2 inflammasome mediated inflammation and pyroptosis promoted pain and inflammation in gouty arthritis." (PMID 39600708, 2024). "Neutrophilic infiltration and subsequent NETosis, a feature of inflamed joint in gout patients 28, exposes self-DNA, which is suspected - once phagocytozed - to induce AIM2-dependent IL-1β secretion (reviewed in 29)." (PMID 32104502, 2020). "Specifically, the AIM2 inflammasome regulated the secretion of inflammatory cytokines, such as IL-1β and IL-18, thereby mediating inflammation and pyroptosis, as well as exacerbating pain and inflammation in gouty arthropathy." (PMID 39600708, 2024).
heart failure (7 papers, 2022 to 2025). Inability of the heart to pump blood at an adequate rate to meet tissue metabolic requirements. "It has been reported that AIM2 inflammasome activation contributes to chronic inflammation in heart failure, with necrotic DNA potentially serving as a major trigger for AIM2 inflammasome activation in vivo." (PMID 38247800, 2024). "An increasing number of studies have shown that the AIM2 inflammasome plays an important and decisive role in cardiovascular diseases, such as aortic aneurysm, coronary atherosclerosis, myocardial infarction, heart failure, ischemia/reperfusion injury and IS." (PMID 39636891, 2024). "Interestingly, AIM2 and NLRC4 were found elevated in cardiac lymphoid cells of failing human hearts; while expression of AIM2 was found in an experimental rodent model of heart failure, further suggesting a role of the inflammasome in the context of adverse cardiac remodeling and heart failure." (PMID 39556309, 2025).